STAT3 (signal transducer and activator of transcription 3)
Diseases named in the same sentence as STAT3 in open-access papers (continued):
Sharing a sentence is not in itself a finding about the gene and the disease.
melanoma (continued). "In conclusion, our study demonstrated that EEF2K plays an oncogenic role in melanoma progression via the p‐STAT3/SPP1 axis." (PMID 35184394, 2022). "Certainly, NF-ҝB and STAT3 play a pivotal role in oncogenesis because they trigger pro-survival signals in many cancer types, including melanoma." (PMID 35163058, 2022). "The STAT3 pathway is frequently upregulated in BRAF inhibitor resistant melanoma, which can drive invasion and metastasis." (PMID 36084109, 2022). "The results were also supported by the findings of a previous study in which TQ treatment reduced the phosphorylation of JAK2 and STAT3 in SK-MEL-28 melanoma cells." (PMID 36145344, 2022). "Taken together, these results suggested that EEF2K promotes melanoma progression through the STAT3/SPP1 pathway." (PMID 35184394, 2022). "A study showed that treatment of melanoma cells with BRAFi induces STAT3-dependent expression of SOX2, which, together with CD24, contributes to create an autoregulatory loop that sustains adaptive resistance to BRAF-targeted therapy." (PMID 35944584, 2022). "As a downstream target of the IFN-γ signaling pathway, the expression levels of STAT3 were increased to 6.3-fold of control when wm115 primary melanoma cells were exposed to IFN-γ (250 units/mL) for 24 h." (PMID 35105915, 2022). "A previous study found that SIPAR promotes the dephosphorylation of STAT3 and further affects the progression of melanoma through physical interaction with STAT3." (PMID 35180853, 2022). "The mechanisms included inhibition of cyclooxygenase-2 (COX-2) and signal transducer and activator of transcription 3 (STAT3) pathway, which are the key targets in melanoma." (PMID 36226570, 2022). "Nilotinib blocks P38 MAPK activation in leukocytes in the liver in wild-type mice and AKT/STAT3 phosphorylation in human melanoma cells." (PMID 35841100, 2022). "Another study also reported that HDAC6 can recruit and activate the signal transducer and activator of transcription 3 (STAT3), which increases the expression of PD-L1 through STAT3-mediated activation of the PD-L1 promoter in melanomas." (PMID 35585975, 2022). "We further show that CDDO-Me attenuates STAT3 phosphorylation in melanoma-conditioned macrophages, and that T cells and CDDO-Me impair myeloid cell migration." (PMID 35265066, 2022). "Our data suggested that silencing STAT3 can downregulate PKM2 expression while activating STAT3 can upregulate PKM2 expression in melanoma cells." (PMID 36188586, 2022). "Addtionally, cilengitide downregulated the expression of PD-L1 on melanoma cells by reducing STAT3 phosphorylation." (PMID 35142593, 2022). "STAT3-/- hosts rejected melanoma (B16), and bladder carcinoma (MB49), and these rejections were dependent on the T cells’ presence." (PMID 35270020, 2022). "Actually, in a mouse model, the silencing of STAT3 expression results in melanoma growth inhibition." (PMID 35163058, 2022). "For example, BBR inhibits MMP-2 and MMP-9 expression by downregulating TGF- β1 and the COX-2/PGE2–JAK2/STAT3 axis in breast cancer, and epithelial-mesenchymal transition in melanoma by inhibition of the RARα/β-mediated PI3K/AKT signaling pathway." (PMID 36678712, 2022). "TQ also demonstrated synergistic effects when combined with radiation in HNSCC through inhibition of proliferation and enhanced the effect of gamma knife on apoptosis and DNA damage in B16-F10 melanoma cells by modulating the JAK2/STAT3 pathway." (PMID 35326517, 2022). "In a different study, the inhibition of the viability and proliferation of A375 and A2058 melanoma cells was shown by the dauricine via blocking the phosphorylation-mediated activation of STAT3 and Src in a dose-dependent manner." (PMID 36224606, 2022). "While quercetin has been shown to inhibit the growth of melanoma cells by blocking the transducer protein and inhibiting the activation of signal transducer and activator of transcription 3 (STAT3) proteins." (PMID 35694174, 2022).
melanoma (continued). "STAT3 inhibition by an Src inhibitor leads to the downregulation of Mcl-1 gene expression in melanoma cells." (PMID 36080130, 2022). "The ability of UV to induce miR-21 overexpression in melanoma involves the ROS-mediated modulation of transcription factors such STAT3, AP-1, and NF-ĸB, which all have recognition sites on the miR-21 promoter." (PMID 35804995, 2022). "CCT196969 seems to be an effective inhibitor of cell viability in EGFR-mutated melanoma, as well as in BRAF inhibitor resistant melanoma which has achieved resistance with upregulation of the STAT3 pathway." (PMID 36084109, 2022). "LHFPL3-AS1 upregulates the miR-181a-5p/BCL2 and miR585/STAT3 feedback loops, which are required for melanoma migration, invasion, and growth in vitro and in vivo and is an unfavorable prognostic marker in melanoma patients." (PMID 35159386, 2022). "The expression of phosphorylated signal transducer and activator of transcription 3 (Stat3), an important immune regulator gene, has been shown to be higher in melanoma brain-metastases relative to distant metastases to the rest of the body." (PMID 36527157, 2022). "In line, STAT3 in a murine melanoma cell line was shown to inhibit the expression of proinflammatory cytokines such as TNFα and IL-12 and the chemokine CCL5." (PMID 35865518, 2022). "Migration and wound healing assays showed that the miR-5100/SPINK5/STAT3 axis promotes melanoma cell metastasis; the mechanism was proven by initiation of epithelial-mesenchymal transition." (PMID 35705923, 2022). "Phosphorylation of STAT3 in melanoma activated by IL-6 can be reversed by co-treatment with apatinib and WZB117." (PMID 36188586, 2022). "The relevance of c-Kit-mediated activation of STAT3 was demonstrated in a Phase II study on the c-Kit inhibitor Nilotinib in melanoma patients." (PMID 35955836, 2022). "Our data agree with other studies showing the prognostic potential of ARG2,22,43, 44, 45 while a recent study showed that ARG2 promotes melanoma progression and metastasis through STAT3 signalling, also involved in BM." (PMID 36423363, 2022). "Several strategies have been used to inhibit the STAT3 pathway as a therapeutic approach for treating malignant melanoma." (PMID 35401182, 2022). "A LHFPL3-AS1/miR-580-3p/STAT3 axis contributes to melanoma development by activating the JAK2/STAT3 pathway." (PMID 35132320, 2022). "FLLL32, a structural analog of curcumin, specifically inhibits STAT3 while retaining STAT1 mediated signal transduction within melanoma and immune-sensitive cells." (PMID 35401182, 2022). "Our study revealed, for the first time, that cilengitide suppressed PD-L1 expression and STAT3 phosphorylation in melanoma, indicating a new therapeutic application for cilengitide." (PMID 35142593, 2022). "For instance, IL-11-mediated STAT3 activation in gastric cancer epithelial cells results in melanoma 2 up-regulation, which promotes epithelial cell migration and development." (PMID 36291659, 2022). "In turn, IL-6 induces STAT3 activation in melanoma cells that upregulates genes involved in tumor angiogenesis and survival." (PMID 36411434, 2022). "This compound has been described to inhibit melanoma growth via inhibition of the JAK2/STAT3 pathway." (PMID 36224606, 2022). "The development of GCs resistance after long-term prednisolone treatment has been observed in human melanoma cells, which showed a two-fold increase in STAT3 expression." (PMID 35252347, 2022). "Our study demonstrated that both the expression levels and activation of STAT1 and STAT3 in melanoma were increased after IFN-γ treatment, which were abolished by co-treatment with nNOS inhibitors." (PMID 35105915, 2022). "Consistently, it has been proposed that melanoma cell-secreted exosomal miR-155-5p can induce the proangiogenic switch of CAFs via the SOCS1/JAK2/STAT3 signaling pathway." (PMID 35443745, 2022). "Treatment of different melanoma cells with FLLL32 triggers caspase-dependent apoptosis via inhibition of STAT3." (PMID 35401182, 2022).
melanoma (continued). "Both studies with melanoma patients in vivo and with the multi-targeted tyrosine kinase inhibitor, sunitinib, demonstrated that STAT3 is essential for the proliferation of MDSC." (PMID 36159871, 2022). "Based on the identified peak, we designed primers for ChIP‐qPCR analysis, aiming to validate that STAT3 binds to the SPP1 promoter in SK‐MEL‐28 melanoma cells." (PMID 35184394, 2022). "Constitutive activation of STAT3 has been demonstrated to be an oncogenic feature in numerous tumours, including melanoma." (PMID 35184394, 2022). "Our results revealed that cilengitide negatively regulated PD-L1 expression in murine and human melanoma cell lines in vitro by decreasing STAT3 phosphorylation." (PMID 35142593, 2022). "Our study reveals that the combination of apatinib and WZB117 displays synergistic anti-tumor activity against melanoma via blocking STAT3/PKM2 axis and is a potential therapeutic strategy for melanoma." (PMID 36188586, 2022). "The activation of Stat3 is upregulated in human brain metastatic cells and contributes to brain metastasis of melanoma." (PMID 36527157, 2022). "Previously, we showed that ONC decreases expression and activity of both NF-κB and STAT3 in A375 melanoma cells." (PMID 35163570, 2022). "The STAT3 pathway is an important target for therapy in the majority of tumors, and it is hyper-activated in cells and tissue samples from melanoma." (PMID 35163058, 2022). "The overexpression of IRE1α or XBP1s enhances IL-6 expression, thereby activating the JAK/STAT3 pathway and promoting melanoma cell proliferation." (PMID 34356855, 2021). "We confirmed that GO-Y030-treatment strongly reduced the survival of B16-F10 melanoma cells and STAT3 activation compared with curcumin treatment." (PMID 34248973, 2021). "Our findings indicate that Tim-3 expression on Treg cells within the TME is STAT3-dependent, providing support to STAT3 as a target and enhancing the immunotherapy for patients suffering from melanoma." (PMID 33936081, 2021). "Elevated levels of acetylation of STAT3 at K685 is known in subjects with melanoma, colon carcinoma and triple negative breast cancer compared to respective normal tissues." (PMID 33604794, 2021). "Our study demonstrated that LRG1 regulates multiple aspects of melanoma metastasis through modulating EGFR/STAT3 signalling." (PMID 34208965, 2021). "Here, we link NLRP3 activity in melanoma cells to the IL-1β induced-IL‐6/STAT3 axis, thus providing an additional mechanism to target STAT3 signaling in melanoma." (PMID 34531850, 2021). "Mechanistically, ERK5 inactivation suppressed the phosphorylation of STAT3, thereby inhibiting the proliferation of melanoma and carcinoma grafts." (PMID 34683963, 2021). "In B16F10 melanoma cells, increased miR-125B acted to suppress tumor cell migration by repressing Stat3 and promoting E-cadherin, while FAK acted to prevent the function of miR-125b." (PMID 34067095, 2021). "Recently, STAT3 signaling was also reported to be involved in LRG1-promoted metastatic dissemination of melanoma." (PMID 34930899, 2021). "Specifically, we discovered that CD27-AS1-208 up-regulation promoted STAT3 pathway, contributing to melanoma growth and progression." (PMID 35096622, 2021). "Overexpression of TRIM14 also increased the number of invasive melanoma cells while blocking AKT or STAT3 pathway did the opposite effects." (PMID 33982666, 2021). "LAG-3+ pDCs possess high potentials in producing IL-6, which suppresses the immune system via STAT3 signaling and leads to melanoma metastasis." (PMID 32902664, 2021). "What’s more, inhibition of AKT or STAT3 pathway partially abolished the growth of melanoma induced by TRIM14 overexpression." (PMID 33982666, 2021). "Melanoma-infiltrated Treg cells exhibited a similar in vitro Tim-3 increasing trend in STAT3 pathways blockade." (PMID 33936081, 2021). "In our study, we reported that STAT3 pathway activation was involved in melanoma malignancy mediated by TRIM14." (PMID 33982666, 2021).
melanoma (continued). "Accumulative evidence has revealed that STAT3 is hyper-activated in melanoma and contributes to tumor initiation and progression through the regulation of cell proliferation, metastasis and immune evasion." (PMID 35096622, 2021). "The results revealed a similar trend of the negative association of various immune cell infiltrations with CDK2, CDK4, and STAT3 SCNA in GBM and CDK2/4/6/STAT3 SCNA in melanoma." (PMID 33668805, 2021). "Treating immune-competent mice bearing mouse melanoma with PS-acet.-STAT3 peptide inhibited STAT3 in tumor-infiltrating T cells, downregulating tumor-infiltrating CD4+ T regulatory cells while activating CD8+ T effector cells." (PMID 33491667, 2021). "Our work indicated that the downregulation of STAT3 decreased melanoma growth in the murine mouse model." (PMID 33936081, 2021). "A number of studies have shown IL-6 and its major effector STAT3 as pro-tumorigenic mediators in many cancers, including melanoma, breast, lung, colon, prostate, ovarian, and hematological cancers, and to be associated with OB–OC coupling via notch signaling." (PMID 34124067, 2021). "Subsequent in vitro functional and mechanistic studies showed that CD27-AS1-208 promoted melanoma cell proliferation, migration and invasion by directly interacting and activating STAT3." (PMID 35096622, 2021). "In this study, enforced PEAK1 expression induces EMT and promotes cell growth and metastasis in vitro and in vivo in melanoma cells through activating JAK/STAT3 signaling." (PMID 34365903, 2021). "Herein, results have demonstrated that STAT3 downregulation in melanoma markedly reduced the proportion of tumor-infiltrated Treg cells." (PMID 33936081, 2021). "MAPK signaling primarily targets JUN that subsequently cooperates with STAT3 upregulating PD-L1 expression in BRAF inhibition (BRAFi)-resistant melanoma and NSCLC, where the signaling cascade is reversible by MEK inhibition (MEKi)." (PMID 34088360, 2021). "In aggregate, CD27-AS1-208 is a novel facilitator in melanoma progression via the activation of STAT3 pathway." (PMID 35096622, 2021). "It has been demonstrated that B7‐H3 expression is enhanced in metastatic melanoma in comparison to primary melanoma and promotes metastasis through the upregulation of cyclin D1, Stat3, and p-Stat3." (PMID 32902664, 2021). "Cumulating evidence has proved the vital role of STAT3 activation in melanoma initiation and progression." (PMID 35096622, 2021). "It is important to define a mechanism for how elevated S100B in malignant melanoma suppresses the IL6/STAT3 pathway." (PMID 34411141, 2021). "To further address the molecular mechanisms triggered in Treg cells upon Tim-3 upregulation, we evaluated a crucial mediator of carcinogenesis STAT3 through immunosuppression in melanoma." (PMID 33936081, 2021). "WP1066, a novel small molecule inhibitor of STAT3, exhibits significant antitumor effect in advanced melanoma patients by inhibiting the proliferation of Tregs and enhancing the TCR activation on ZAP-70." (PMID 34806028, 2021). "HDAC6 causes STAT3 phosphorylation, where HDAC6 and phospho-STAT3 are then recruited to the CD274 promoter, mediating the upregulation of PD-L1 in melanoma." (PMID 34088360, 2021). "As such, targeting STAT3 has been considered a promising therapeutic strategy for highly metastatic melanoma." (PMID 34208965, 2021). "Collectively this study suggested that the immune cell infiltrations of GBM and melanoma are inversely associated with CDK2/4/6 and STAT3 expression or genetic alterations." (PMID 33668805, 2021). "STAT3 activity is higher in human brain metastatic cells than in primary melanoma cells, and its activation induces angiogenesis, cell invasion, MMP-2 secretion, cytokine expression, and immune suppression, that contribute to their brain metastatic potential." (PMID 33466236, 2021). "IL-6 sends signals directly to melanoma cells through the JAK/STAT3 pathway, which leads to increased tumor production (immunosuppressive cytokines)." (PMID 33540700, 2021).